ANXA8 (annexin A8)
Diseases named in the same sentence as ANXA8 in open-access papers (continued):
Sharing a sentence is not in itself a finding about the gene and the disease.
gastric cancer (5 papers, 2012 to 2025). A primary or metastatic malignant neoplasm involving the stomach. "In gastric cancer, high ANXA8 expression is closely associated with advanced TNM stage and poor differentiation, indicating a worse prognosis for patients." (PMID 39716068, 2024). "Large-scale clinical data further confirmed the correlation between ANXA8 expression and both gastric cancer progression and 5-FU therapeutic efficacy." (PMID 40862051, 2025). "Meanwhile, ANXA8 overexpression in gastric cancer has been correlated with disease stage and differentiation grading, and it emerged as an independent predictor of worse OS and DFS and a potential poor prognosis biomarker for gastric cancer patients." (PMID 36247003, 2022).
acute promyelocytic leukemia (4 papers, 2019 to 2023). An aggressive form of acute myeloid leukemia (AML), characterized by arrest of leukocyte differentiation at the promyelocyte stage, due to a specific chromosomal translocation t(15;17) in myeloid cells. "AnxA8 levels are upregulated by leptin, during mammary gland involution and in acute promyelocytic leukemia (APL) cells." (PMID 33810523, 2021). "ANXA8 upregulation was found upregulated for the first time in acute promyelocytic leukemia (APL) with repressed wild-type RARA transcriptional function due to dominant negative RARA fusion proteins as PML-RARA." (PMID 30678048, 2019). "The first cancer showing ANXA8 upregulation was reported in acute promyelocytic leukemia (APL), which induces the differentiation arrest of promyelocytes due to defective RA signaling caused by RARA fusion genes as the PML-RARA gene." (PMID 32823855, 2020). "This review focuses on cancers expressing well-known annexins, with a special emphasis on ANXA8, which is an annexin that was found to be overexpressed for the first time in acute promyelocytic leukemia (APL) carrying a fusion gene involving both PML and RARA." (PMID 32823855, 2020).
lymph node metastasis (4 papers, 2016 to 2020). "Studies have shown that ANXA8 is a molecular marker associated with lymph node metastasis in oral squamous cell carcinoma." (PMID 33166290, 2020). "Furthermore, ANXA8 expression (HR 2.151, 95% CI 1.299-3.562, p=0.0029) and lymph node metastasis (HR 2.027, 95% CI 1.227-3.348, p=0.0058) were associated with DFS." (PMID 32284751, 2020). "Multivariate analysis indicated that ANXA8 expression (HR 2.293, 95% CI 1.317-3.991, p=0.003), lymph node metastasis (HR 3.572, 95% CI 2.047-6.233, p<0.001) and differentiation grade (HR 2.137, 95% CI 1.006-2.794, p=0.047) were associated with OS." (PMID 32284751, 2020).
oral squamous cell carcinoma (3 papers, 2016 to 2023). "The high expression of ANXA8 is also associated with oral squamous cell carcinoma (OSCC) by metastasizing the cervical lymph node, suggesting potential treatment avenues." (PMID 37555363, 2023).
cervical cancer (2 papers, 2022 to 2024). A primary or metastatic malignant neoplasm involving the cervix. "In this respect, inhibition of miR185-3p promotes AnxA8 expression while increased miR185-3p levels reduce AnxA8 expression and inhibit proliferation in cervical cancer cells." (PMID 36313572, 2022). "Regarding cervical cancer, reports demonstrate that ANXA8 is significantly expressed in squamous cell carcinoma but not evidently in adenocarcinoma, suggesting its potential as a molecular marker to differentiate between cervical squamous cell carcinoma and adenocarcinoma." (PMID 38952985, 2024). "In the immunohistochemical staining of DSP, PPP1R13L and ANXA8 in paracancer and cervical cancer tissues, the staining intensity of three proteins in cancer tissues was found to be enhanced, primarily expressed in the cytoplasm and cell membrane compared with paracancer control." (PMID 38952985, 2024). "Additionally, three differential proteins, DSP, PPP1R13L and ANXA8, were selected, and their possible promoting roles in the occurrence and development of cervical cancer were speculated upon." (PMID 38952985, 2024). "Immunohistochemistry and western blotting of cervical squamous cell carcinoma tissue slices with antibodies against DSP, PPP1R13L and ANXA8 is conducted, hypothesizing these proteins’ fundamental roles in the regulation and progression of cervical cancer cells." (PMID 38952985, 2024).
ductal carcinoma in situ (2 papers, 2020 to 2022). "Higher ANXA8 in ductal carcinoma in situ (DCIS) versus atypical ductal hyperplasia (ADH) and normal breast tissue was detected in tissue microarrays." (PMID 32823855, 2020). "Consistently, ANXA8 upregulation was confirmed to be highly expressed in breast DCIS relative to ADH and normal breast tissue, as well as in 3D human mammary epithelial cell models of ductal carcinoma in situ (DCIS)." (PMID 32823855, 2020).
Hypertension (2 papers, 2023 to 2024). The presence of chronic increased pressure in the systemic arterial system. "Anxa8 was identified to play an important role for the induction of hypertension in salt-sensitive rats." (PMID 37660920, 2023). "Meanwhile, NONRATG012674.2, which is overexpressed in the high salt sensitivity group, could interact with key hypertension genes like Anxa8, Hspa5, and Krt15, with Hspa5 being part of the HSP70 family associated with hypertension and inflammation." (PMID 38791545, 2024).
Obesity (2 papers, 2025 to 2026). Accumulation of substantial excess body fat. "Lastly, our study identifies several differently regulated proteins whose role in obesity and adipose tissue is poorly known, such as ANXA8, DDX39B, STX7, SYNCRIP, SYNGR2, and PAK2." (PMID 41077621, 2026). "Moreover, ANXA8 expression, previously reported to be similar in SAT and VAT of men with obesity, has been associated with cellular dysfunction when dysregulated." (PMID 41077621, 2026). "Thus, although the function of ANXA8 is not well known, our findings suggest that its expression profile may play a role in alterations of VAT cholesterol metabolism in obesity." (PMID 41077621, 2026).
antiphospholipid syndrome (1 paper, 2018). A disorder caused by the presence of autoantibodies directed against phospholipids, causing a hypercoaguable state, which may result in blood clots, stroke, heart attack, and in women, significant pregnancy-related complications, including miscarriage and still birth. "Antibodies specific for annexin A8 (AnxA8) have not been investigated in patients suffering from antiphospholipid syndrome (APS) yet." (PMID 30429671, 2018).
atherosclerosis (1 paper, 2025). A disease characterized by the build-up of fatty material and calcium deposition in the arterial wall resulting in partial or complete occlusion of the arterial lumen. "ApoE−/− mice lacking systemic AnxA8 (ApoE−/−AnxA8−/−) were generated to assess the effect of AnxA8 deficiency on atherosclerosis." (PMID 39835780, 2025). "The delayed progression of atherosclerosis observed in AnxA8‐deficient mice appears to be the result of reduced inflammatory cell content in plaques." (PMID 39835780, 2025). "The finding that the germline AnxA8 deficiency drastically reduces the atherosclerotic burden in both early and advanced atherosclerosis in an ApoE−/− mouse model argues for a functional role of AnxA8 in the progression of atherosclerosis." (PMID 39835780, 2025). "Since the phenotypic switch of vascular cells also plays an important role in atherosclerosis progression, we examined whether AnxA8 deficiency influences VSMCs phenotype." (PMID 39835780, 2025). "Our work demonstrates a pathogenic role of endothelial Annexin A8 in atherosclerosis." (PMID 39835780, 2025). "We have shown an upregulation of AnxA8 in both human and murine atherosclerotic plaques, identifying AnxA8 as an important mediator of atherosclerosis." (PMID 39835780, 2025). "To analyse the contribution of endothelial AnxA8 in the progression of atherosclerosis, we used pAAV2‐QuadYF, an adenovirus that shows a specific tissue tropism for ECs and retina." (PMID 39835780, 2025). "To analyse the contribution of AnxA8 in the progression of atherosclerosis, we bred AnxA8−/− mice with the atheroprone mouse model, ApoE−/−, to generate ApoE−/−AnxA8−/− mice." (PMID 39835780, 2025). "Our findings demonstrate that AnxA8 promotes the progression of atherosclerosis by modulating endothelial−leukocyte interactions." (PMID 39835780, 2025). "Altogether, our results indicate an essential role of endothelial AnxA8 in atherosclerosis progression." (PMID 39835780, 2025). "Since inflammatory cell recruitment is a key event in atherosclerosis, here we investigated the importance of AnxA8 in atherogenesis and identified a prominent deleterious effect on plaque development and progression." (PMID 39835780, 2025). "However, our data show that AnxA8 does not play a direct role in VSMC phenotypic switching or macrophage lipid metabolism, supporting the potential role of endothelial AnxA8 in atherosclerosis." (PMID 39835780, 2025). "In addition, circulating P/E selectin and CD31 concentrations were diminished in serum of ApoE−/−AnxA8−/− compared with ApoE−/− AnxA8+/+ mice in either the early or the advanced model of atherosclerosis." (PMID 39835780, 2025). "Since our results indicated that AnxA8 deficiency in hematopoietic cells does not play a significant role in atherosclerosis, we next analysed AnxA8 expression in resident cells, specifically VSMCs and ECs." (PMID 39835780, 2025). "Since LDL retention in the arterial wall is one of the key processes in atherosclerosis progression, we performed in vivo LDL retention experiments to analyse whether AnxA8 deficiency affects lipoprotein retention." (PMID 39835780, 2025). "Therapeutic interventions to reduce AnxA8 expression in endothelial cells may delay atherosclerosis progression." (PMID 39835780, 2025). "Finally, endothelial‐specific silencing of AnxA8 decreased atherosclerosis progression." (PMID 39835780, 2025). "Oxidized LDL activates ECs by promoting the expression and secretion of a variety of adhesion molecules and chemotactic factors at atherosclerosis‐prone sites, and we have shown that ox‐LDL upregulates AnxA8 expression in ECs in a time‐ and dose‐dependent manner." (PMID 39835780, 2025).
bladder tumors (1 paper, 2021). "ANXA2, ANXA3, ANXA4, ANXA8, and ANXA9 were significantly increased in bladder tumor tissues, while ANXA6, ANXA7, and ANXA11 were significantly decreased." (PMID 34484309, 2021).
cervical squamous cell carcinoma (1 paper, 2024). A squamous cell carcinoma arising from the cervical epithelium. "This proteomic data, derived from cervical squamous cell carcinoma cells, indeed detected the upregulation of ANXA8, hypothesizing that ANXA8, as an up-regulated protein, plays a significant role in cervical squamous cell carcinoma." (PMID 38952985, 2024).
clear cell carcinoma (1 paper, 2019). "ANXA8 showed the highest high positive rate (87.50%) in clear cell carcinoma and the lowest high positive rate in mucinous cystadenocarcinoma (55.56%)." (PMID 31474227, 2019).
hepatic disease (1 paper, 2015). "These genes encode for omentin (intelectin 1), claudin 1, polycystic kidney and hepatic disease 1 (autosomal recessive)-like 1, and annexin A8." (PMID 26636677, 2015).
lung adenocarcinoma (1 paper, 2025). A carcinoma that arises from the lung and is characterized by the presence of malignant glandular epithelial cells. "For example, LAMC2, which drives EMT and metastasis in lung adenocarcinoma, and ANXA8, which is upregulated in various cancers including PM, could serve as important diagnostic tools." (PMID 39920655, 2025).
myelocytic leukaemias (1 paper, 2015). "AnxA8 was specifically up-regulated in APL but not in other myelocytic leukaemias." (PMID 25803307, 2015).
non-small cell lung carcinoma (1 paper, 2024). A group of at least three distinct histological types of lung cancer, including non-small cell squamous cell carcinoma, adenocarcinoma, and large cell carcinoma. "ANXA8 regulates the proliferation of human non-small cell lung cancer cells A549 through the EGFR-AKT-mTOR signaling pathway." (PMID 38952985, 2024).
oral cancer (1 paper, 2023). "All of these pieces of evidences may indicate that the ANXA8 may play a crucial role in inflammation, cell apoptosis, and oral cancer." (PMID 37555363, 2023).
ovarian serous tumor (1 paper, 2019). A benign, borderline, or malignant epithelial tumor of the ovary characterized by the presence of neoplastic epithelial cells that, in well differentiated tumors, resemble the epithelial cells of the fallopian tube and, in poorly differentiated tumors, show anaplastic features. "Prognostic analysis suggested that significant correlations occurred between ANXA2/4/8/9 mRNA upregulation and poor overall survival, and between ANXA8/9/11 mRNA upregulation and poor progression-free survival in patients with ovarian serous tumors." (PMID 31474227, 2019). "We further analyzed ANXA8, which was significantly correlated with the prognosis of patients with ovarian serous tumors." (PMID 31474227, 2019). "The results of the prognostic analysis showed that, among Annexin family members, the upregulation of ANXA8 mRNA expression displayed the greatest correlation with poor OS and PFS in patients with ovarian serous tumors." (PMID 31474227, 2019). "Taken together, these data indicated that the upregulation of ANXA8 and ANXA9 mRNAs was significantly correlated with poor OS and PFS in patients with ovarian serous tumors." (PMID 31474227, 2019). "Upregulation of ANXA2, ANXA4, ANXA8, and ANXA9 mRNAs displayed significant correlations with poor OS in patients with ovarian serous tumors." (PMID 31474227, 2019).
triple-negative breast carcinoma (1 paper, 2020). An invasive breast carcinoma which is negative for expression of estrogen receptor (ER), progesterone receptor (PR), and human epidermal growth factor receptor 2 (HER2). "RA via RARA can induce baseline ANXA8 protein expression by regulating the transcription of specific miRNAs targeting the ANXA8 mRNA 3′untranslated region (3′UTR), including miR-218 associated with breast DCIS and miR-342 associated with triple negative breast cancer (TNBC)." (PMID 32823855, 2020).
cancer (19 papers, 2012 to 2025). A tumor composed of atypical neoplastic, often pleomorphic cells that invade other tissues. "Most deregulated genes have been reported as potentially implicated in cancer and severals, as ANXA8 and FBN1, are highlighted by both, mRNA and miRNA analyses." (PMID 23593401, 2013). "Elevated ANXA8 expression has been implicated in the progression and metastasis of various cancers." (PMID 39716068, 2024). "After the original discovery of ANXA8 in classical APL several decades ago, research focusing on the role of ANXA8 in different cancers will be indispensable not only for developing diagnostic and prognostic biomarkers, but also for devising ad hoc therapeutic strategies." (PMID 32823855, 2020). "Over expression of ANXA8 has been reported to be associated with cancer and apoptosis." (PMID 24633136, 2014). "Since ANXA8 protein is an underlying therapeutic target for a variety of cancers, it has received much attention in the medical community in recent years and may be used as a model for the study of human cancer." (PMID 39068672, 2024). "Mechanistically, ANXA8 interacts with SP1 to promote the transcription of pyrophosphatase 1, thereby suppressing the TCA cycle, activating cancer-associated fibroblasts, and facilitating aberrant ECM deposition." (PMID 40862051, 2025). "To further verify the validity of the data, we used GEPIA database to validate the expression of DSP, PPP1R13L and ANXA8 in human cancers and normal cervix." (PMID 38952985, 2024). "To further verify the validity of the data, we used the GEPIA database to validate the expression of DSP, PPP1R13L and ANXA8 in human cancers and normal cervix." (PMID 38952985, 2024). "All these features make ANXA8 an important regulator of key cellular processes such as migration, invasion and adhesion, often commonly dysregulated in cancer." (PMID 36247003, 2022). "The focus of this review is on emerging RA-regulated mechanisms involving specific annexins in APL and other cancers, with a special emphasis on cancers over-expressing ANXA8." (PMID 32823855, 2020). "It is noteworthy that APL was the first cancer showing the dysregulation of ANXA8, which is a member of the Annexin family of calcium (Ca2+) and phospholipid binding proteins involved in several cellular functions." (PMID 32823855, 2020). "Immunocytochemistry showed that ANXA8 expression was higher in the malignant tumor group relative to borderline, benign, and normal groups." (PMID 32823855, 2020). "Previous studies have shown that the expression of ANXA8 is elevated in various types of cancer tissues while limited in normal tissues." (PMID 32284751, 2020). "Moreover, we used GEPIA database to validate the expression of DSP, PPP1R13L and ANXA8 in human cancers and normal cervix." (PMID 38952985, 2024). "Inhibition of ANXA8 expression in OC cells could significantly inhibit cell proliferation, invasion, migration and promote apoptosis of cancer cells, which is consistent with a previous study." (PMID 39068672, 2024). "Cancer-related articles have corroborated ANXA8’s involvement in signal transduction functions." (PMID 38952985, 2024). "ANXA8 mainly acts as a tumor-promoting gene in human cancers." (PMID 36247003, 2022). "On a similar note, ANXA8 had been revealed to be upregulated in various cancers." (PMID 35480879, 2022). "The feedback loop between RA-RARA and ANXA8 fostered cancer initiation and progression." (PMID 35480879, 2022). "Thus, ANXA8 is expected to be a new biomarker and molecular therapeutic target for the diagnosis, treatments and prognosis of multiple diseases, especially malignant tumors." (PMID 32284751, 2020). "For instance, cancers expressing ANXA8 might be targeted with a strategy developed for targeting ANXA2." (PMID 32823855, 2020). "Recently, several studies detecting ANXA8 upregulation in different cancers have been published." (PMID 32823855, 2020).
cancer (continued). "To investigate the specific mechanisms by which ANXA8 regulates the TCA cycle and ECM, we utilized multi-omics data to identify genes highly expressed in cancer tissues." (PMID 40862051, 2025). "In our study, upregulation of ANXA8 resulted in enhanced proliferation capacity and colony formation of NSCLC cancer cells, as well as increased invasive and migratory capabilities." (PMID 39716068, 2024). "COL27A1, PRUNE2, MAEA, TBC1D3, GADD45B, ANXA8 and TSPY1 have been confirmed to play a pro‐resistant role in various cancers, which reflects the reliability of the hGeCKO library screening to some extent." (PMID 39550701, 2024). "Over the years, ANXA8 has also been found to be upregulated in other cancers, even in the absence of RARA fusion genes." (PMID 32823855, 2020).